ZDHHC3 (zDHHC palmitoyltransferase 3)
Diseases named in the same sentence as ZDHHC3 in open-access papers (continued):
Sharing a sentence is not in itself a finding about the gene and the disease.
cognitive disorder (1 paper, 2017). A disease affects cognitive processes. "Our data reveal a key role of FoxO3a/Zdhhc3/GluA1 axis in the HFD-dependent impairment of cognitive function and identify a novel mechanism underlying the cross talk between metabolic and cognitive disorders." (PMID 29222408, 2017). "Collectively, our findings point to the key role of both zDHHC3 overexpression and AMPAR hyper-palmitoylation in the cognitive impairment induced by HFD." (PMID 29222408, 2017).
congestive heart failure (1 paper, 2023). Failure of the heart to pump a sufficient amount of blood to meet the needs of the body tissues, resulting in tissue congestion and edema. "Taken together, these data demonstrate the expression of zDHHC3 S-acyltransferase activity in adult cardiomyocytes causes congestive heart failure." (PMID 37926281, 2023).
demyelination (1 paper, 2024). "Together, our findings propose that dysregulated ZDHHC3-Cadm4 signaling contributes to myelin abnormalities, suggesting a common pathological mechanism underlying demyelination diseases associated with neuroinflammation." (PMID 39327467, 2024). "Moreover, the axis of ZDHHC3-Cadm4 palmitoylation may underlie varied types of demyelination diseases related to neuroinflammation and thus a potential target for intervention." (PMID 39327467, 2024).
demyelination diseases (1 paper, 2024). "This neuroinflammation correlates with impaired cognitive functions and suggests that disruptions in the ZDHHC3-Cadm4 palmitoylation axis may contribute to the pathogenesis of several demyelinating diseases." (PMID 39327467, 2024). "Importantly, attenuated ZDHHC3-Cadm4 signaling significantly influences neuroinflammation in diverse demyelination diseases." (PMID 39327467, 2024). "Interestingly, our data showed that the levels of palm-Cadm4 and ZDHHC3 are downregulated in both LPS and EAE models, suggesting that ZDHHC3-Cadm4 signaling may represent a conserved pathological mechanism underlying various demyelination diseases." (PMID 39327467, 2024).
non-alcoholic fatty liver disease (1 paper, 2025). "The palmitoyltransferase ZDHHC3 exacerbates non-alcoholic fatty liver disease (NAFLD) by promoting the S-palmitoylation of inactive rhomboid protein 2, further highlighting the broader implications of palmitoylation in inflammatory conditions." (PMID 40292278, 2025).
prostate tumor (1 paper, 2023). "ZDHHC3‐mediated palmitoylation plays a key role in regulating the expression, stability, and function of integrin α6β4, and knockdown of ZDHHC3 with shRNA affects integrin‐dependent cable formation and signaling in prostate tumor cells." (PMID 36018061, 2023).
renal cell carcinoma (1 paper, 2024). "We identified 202 hub genes that were most relevant to high zDHHC3 expression and KIRC, and found that they were involved mainly in ion transport and renal cell carcinoma." (PMID 38619631, 2024).
steatosis (1 paper, 2023). Increased lipid within the cytoplasm of cells. "In animal models with NASH, ZDHHC3 performed acceleration of pro‐inflammation, steatosis, and early fibrosis formation by increasing S‐palmitoylation‐stabilized IRHOM2 along with decrease in proteasome degradation of IRHOM2." (PMID 37544908, 2023).
tumor (24 papers, 2020 to 2026). "The integrin α6β4, implicated in tumor progression, metastasis, and angiogenesis, was reported to be S‐acylated by the enzyme zDHHC3 in breast and PCa cell lines." (PMID 39429488, 2024). "ALKBH5 deficiency decreased PD-L1 protein level by suppressing ZDHHC3 mRNA expression in an m6A modification manner, further remodeling the tumor immune microenvironment." (PMID 36566230, 2022). "In addition, a study developed cell-penetrating peptide-induced chimera conjugates to degrade ZDHHC3, thereby directly associating ZDHHC3-mediated PD-L1 palmitoylation with the stability of PD-L1 on tumour cells." (PMID 40657375, 2025). "Additionally, zDHHC3‐suppressed tumors exhibited increased recruitment of innate immune cells associated with senescent tumor clearance." (PMID 39429488, 2024). "The first is to target tumor ZDHHC3 to abolish B7-H4 palmitoylation, thereby destabilizing the B7-H4 protein." (PMID 40341398, 2025). "Knockdown of ZDHHC3 in tumors results in robust anti-tumor immunity and reduces tumor progression in murine models." (PMID 40341398, 2025). "In tumor cells, DHHC3 (ZDHHC3) catalyzes PD-L1 palmitoylation to facilitate its plasma membrane localization and prevent lysosomal degradation." (PMID 40977744, 2025). "We next investigated the role of ZDHHC3 in tumor immunity in a syngeneic immune-competent mouse model." (PMID 40341398, 2025). "zDHHC3 is the primary acyltransferase responsible for PD-L1 S-palmitoylation, and inhibiting PD-L1 S-palmitoylation using 2-BP or silencing DHHC3 activates anti-tumor immunity in CRC." (PMID 38415253, 2024). "zDHHC3-mediated palmitoylation modification plays a crucial role in regulating tumor immune evasion and tumor cell survival." (PMID 39563863, 2024). "After removing the outliers, we included 251 (206 tumor and 45 healthy, 180 low and 71 high zDHHC3 expression) samples in the subsequent analysis." (PMID 38619631, 2024). "In fact, palmitoylation of PD-L1, mainly catalyzed by palmitoyltransferase ZDHHC3 (DHHC3), leads to suppression of PD-L1 ubiquitination and degradation, resulting in protein stabilization, eventually promoting tumor immune escape." (PMID 33114576, 2020). "Additionally, it has been reported that ZDHHC3 can increase tumor cell resistance to oxidative stress and enhance tumor PD-L1 expression, contributing to tumor progression." (PMID 40341398, 2025). "Therefore, zDHHC3-mediated palmitoylation modification regulates the stability and function of PD-L1, influencing tumor immune evasion and survival." (PMID 39563863, 2024). "zDHHC3 is also known to modulate the S-palmitoylation of programmed cell death ligand 1 (PD-L1), and the blocking of PD-L1 S-palmitoylation increased the sensitivity of tumor cells to T-cell cytotoxicity." (PMID 38619631, 2024). "PD‐L1 is specifically palmitoylated at Cys272 by ZDHHC3 in human colorectal cancer cell lines; inhibiting such palmitoylation promotes ubiquitin‐mediated protein degradation of PD‐L1, thereby activating antitumor immunity and significantly suppressing tumor growth." (PMID 36018061, 2023). "In support of this possibility, knocking down ZDHHC3 (shZdhhc3) in 4H11 cells failed to alter tumor cell proliferation in vitro, but reduced B7-H4 expression, and inhibited tumor growth in immune-competent mice." (PMID 40341398, 2025). "In pancreatic cancer, knockdown of ZDHHC3 impaired tumor progression in a xenograft mice model, whereas inactivation of ZDHHC9 modified the tumor microenvironment from an immunosuppressive to a proinflammatory environment and, thus, suppressed tumor growth." (PMID 37759431, 2023). "As ZDHHC3 is responsible for adding palmitoyl moiety to B7-H4, thereby stabilizing B7-H4 protein, we theorized that the absence of ZDHHC3 could slow down tumor progression." (PMID 40341398, 2025).
cancer (17 papers, 2019 to 2026). A tumor composed of atypical neoplastic, often pleomorphic cells that invade other tissues. "Although data on ZDHHC expression in MDA-MB-231 cells remain limited, studies have implicated ZDHHC3, 5, 15, and 20 in cancer-related S-acylation processes." (PMID 41223946, 2025). "Thus, the changes in the ion transport caused by high zDHHC3 expression play an essential role in cancer." (PMID 38619631, 2024). "zDHHC3 has been implicated in various cancers, but its specific role in KIRC remains unclear." (PMID 38619631, 2024). "ZDHHC3 ablation, in combination with chemotherapy, enhances anti-cancer cell activities, not only by increasing oxidative stress but also by enhancing the anti-growth effects of chemotherapeutic agents." (PMID 40814339, 2025). "In the current study, immunohistochemical staining results from the Human Protein Atlas database revealed that ZDHHC3 is widely expressed in various cancer types." (PMID 39349454, 2024). "As a regulatory enzyme for protein S-palmitoylation, zDHHC3 has been shown to play a critical role in the initiation and progression of many cancers." (PMID 38619631, 2024). "PD-L1 and ZDHHC3 were significantly and positively correlated in pan-cancer, BRCA, CES, HNSC, and SKCM patients." (PMID 39349454, 2024). "We analyzed the expression of zDHHC3 in 32 human cancers to explore its potential roles in cancer-suppressing or carcinogenic effects." (PMID 38619631, 2024). "We identified 4918 DEGs and found that zDHHC3 was significantly down-regulated in cancer cells relative to healthy cells." (PMID 38619631, 2024). "In this study, we performed a pan-cancer analysis, bioinformatics analysis, and cell experiment to detect the role of zDHHC3 in KIRC." (PMID 38619631, 2024). "For instance, several different types of cancers have been shown to have excessive ZDHHC3 expression, such as breast cancer." (PMID 38177255, 2024). "zDHHC3 knockout accelerated the degradation of laminin-binding integrin α6β4 in various cancer cells, affecting cancer progression, metastasis, and angiogenesis." (PMID 38619631, 2024). "Elevated ZDHHC3 gene expression correlates with diminished patient survival in at least seven different cancer types." (PMID 35624824, 2022). "Given that ZDHHC3 mediates B7-H4 palmitoylation, palmitoylation stabilizes total and cell membrane B7-H4 expression, and B7-H4 is degraded in lysosome, we suggest two alternatives to target B7-H4 for cancer immunotherapy." (PMID 40341398, 2025). "Given the importance of PD-1 and PD-L1 in both cancer cells and immune cells, polypeptide sequences containing PD-L1 palmitoylation sites were developed to inhibit the palmitoylation of endogenous PD-L1 by competitively binding to ZDHHC3." (PMID 40814339, 2025). "In addition, the correlation analysis between PD-L1 and ZDHHC3 across TCGA cancer samples revealed the potential co-expression pattern and positive correlation between PD-L1 and ZDHHC3 in various cancer types." (PMID 39349454, 2024). "Patients with an elevated expression of ZDHHC3 were associated with worse survival in BRCA, suggesting that ZDHHC3 might be a cancer target." (PMID 36286021, 2022). "Palmitoylation mediated by the palmitoyltransferase zinc finger DHHC-Type palmitoyltransferase 3 (ZDHHC3) in the cytoplasmic domain of PD-L1 blocks its ubiquitination to stabilize PD-L1, thereby, suppressing PD-L1 degradation by lysosomes and PD-L1-mediated immune evasion in cancer." (PMID 35004688, 2021). "The difference in the effect of high zDHHC3 levels in KIRC and other cancers may be due to differences in palmitoylated substrate proteins." (PMID 38619631, 2024). "Remarkably, irrespective of the cancer type, more than half of the patients exhibit high ZDHHC3 protein expression levels." (PMID 39349454, 2024).
infection (2 papers, 2023 to 2026). The state of being infected such as from the introduction of a foreign agent such as serum, vaccine, antigenic substance or organism. "In vivo, ZDHHC3 mRNA is upregulated in splenic macrophages during infection, and 2-bromopalmitate (2BP) treatment reduces bacterial burden in mice, associated with elevated TNF-α and IFN-γ." (PMID 41486271, 2026).
cardiac disease (1 paper, 2023). "Cardiomyocyte-specific transgenic mice overexpressing zDHHC3 show cardiac disease, and S-acyl proteomics identified the small GTPase Rac1 as a novel substrate of zDHHC3." (PMID 37926281, 2023).
ZDHHC3 also shares sentences with these, for which no sentence is quoted: colon cancer (2 papers); melanoma (2); breast tumour (1); Ewing sarcoma (1); experimental autoimmune encephalomyelitis (1); glioblastoma (1); Hepatic fibrosis (1); hepatocellular carcinoma (1); kidney clear cell carcinoma (1); leukemia (1); metabolic disorder (1); metabolic syndrome (1); neurodegenerative disease (1); neurological diseases (1); ovarian carcinoma (1); prostate adenocarcinoma (1); skin cancer (1).